MIR3680-2 (microRNA 3680-2)
Synonyms: hsa-mir-3680-2
Gene: MicroRNA gene on chromosome 16 (29,599,179 to 29,599,265, reverse strand). Ensembl gene ENSG00000266758.
Homologues: Orthologues: chimpanzee MIR3680-2 (100% identical). Paralogues in human: MIR3680-1 (100% identical).